SYT1 (synaptotagmin 1)
Diseases named in the same sentence as SYT1 in open-access papers (continued):
Sharing a sentence is not in itself a finding about the gene and the disease.
Stroke (2 papers, 2019 to 2021). Sudden impairment of blood flow to a part of the brain due to occlusion or rupture of an artery to the brain. "Moreover, potential biomarkers like Syt1 and Idh3a could be considered to be applied in clinical practice for early identification of cold wave-related stroke among inpatients during cold waves, and prophylactic drugs like batroxobin for treatment of cold wave-related stroke." (PMID 34086602, 2021).
temporal lobe epilepsy (2 papers, 2012 to 2024). A localization-related (focal) form of epilepsy characterized by recurrent seizures that arise from foci within the temporal lobe, most commonly from its mesial aspect. "A dysregulation of hippocampal Syt1 expression was also reported in patients with mesial temporal lobe epilepsy, where it decreased and in the refractory group of patients of temporal lobe epilepsy, where it increased." (PMID 23236410, 2012).
thyroid cancer (2 papers, 2024 to 2025). "Promoting thyroid cancer cell proliferation and metastasis by miRNA-363-3p is facilitated through the mediation of SYT1 to suppress autophagy." (PMID 39281375, 2024).
acute myocardial infarction (1 paper, 2025). Necrosis of the myocardium, as a result of interruption of the blood supply to the area. "This property of Syt1 was used to synthesize an extracellular molecular probe for SPECT imaging of cardiac cell death in acute myocardial infarction." (PMID 39865120, 2025). "Syt1 is highly expressed in cardiomyocytes and has been used as an extracellular molecular probe for SPECT imaging of cardiac cell death in acute myocardial infarction." (PMID 39865120, 2025).
autoimmune disease (1 paper, 2012). A disorder resulting from loss of function or tissue destruction of an organ or multiple organs, arising from humoral or cellular immune responses of the individual to their own tissue constituents. "Identification of synaptotagmin-1, the first cell membrane associated autoantigen in this spontaneous autoimmune disease, demonstrated that examination of tissue fractions can lead to the discovery of previously undetected novel autoantigens." (PMID 23236410, 2012).
Brain atrophy (1 paper, 2024). Partial or complete wasting (loss) of brain tissue that was once present. "The results showed that GAP43, SNAP25, neurogranin, and synaptotagmin 1 were decreased in neuronal-derived EVs but increased in CSF in patients with AD, and the changes corresponded to the severity of brain atrophy." (PMID 38528511, 2024). "In the present study, we demonstrated that GAP43, neurogranin, SNAP25, and synaptotagmin 1 were significantly changed in both EVs and CSF in patients with AD, and these changes corresponded to the severity of brain atrophy." (PMID 38528511, 2024).
cardiac hypertrophy (1 paper, 2025). "SYT1 deficiency aggravates pressure overload-induced cardiac hypertrophy, fibrosis, dysfunction, and cardiomyocyte apoptosis mainly by activating the p38 MAPK pathway." (PMID 40279007, 2025). "We conclude that deficiency of SYT1 aggravates pressure overload-induced cardiac hypertrophy via the p38 MAPK signaling pathway." (PMID 40279007, 2025). "We discovered that SYT1 was expressed in mice ventricles and H9C2 cardiomyocytes; SYT1 KO exacerbated TAC-induced cardiac hypertrophy in mice; SYT1 silencing also exacerbated Ang II-induced cardiomyocyte hypertrophy and apoptosis." (PMID 40279007, 2025). "We observed here that SYT1 deficiency exacerbated cardiac hypertrophy in vivo and cardiomyocyte hypertrophy in vitro, suggesting that SYT1 has a function of repressing pressure overload-induced cardiac hypertrophy." (PMID 40279007, 2025). "In the present study, we generated a Syt1+/− mice strain and used it to assess the potential role of SYT1 in cardiac hypertrophy." (PMID 40279007, 2025). "The present study aimed to investigate the expression and function of SYT1 in the development of cardiac hypertrophy both in vivo and in vitro." (PMID 40279007, 2025). "In summary, the present study identified a previously unrecognized biological function of SYT1 in cardiac hypertrophy." (PMID 40279007, 2025). "We found that the SYT1 expression levels were significantly upregulated in both the mouse model of TAC-induced cardiac hypertrophy and in the H9C2 cardiomyocyte model of Ang II-induced hypertrophy." (PMID 40279007, 2025). "Mechanistic experiments showed that the aggravation of TAC-induced cardiac hypertrophy and dysfunction by SYT1 KO or silencing is mediated by activated p38 MAPK signaling pathway, the major pathway that induces cardiac hypertrophy." (PMID 40279007, 2025). "Syt1+/− mice showed significantly exacerbated cardiac hypertrophy, dysfunction, fibrosis, apoptosis and phosphorylation of myocardial p38 MAPK in response to TAC compared to WT mice." (PMID 40279007, 2025). "The study suggests a protective role of SYT1 in cardiac hypertrophy and provides promising therapeutic targets for cardiac hypertrophy." (PMID 40279007, 2025). "Because apoptosis is an important character of cardiac pathological remodeling, and SYT1 contributes to apoptosis, we therefore examined the potential role of SYT1 in cardiomyocyte apoptosis in cardiac hypertrophy." (PMID 40279007, 2025). "Here, we investigated the role and mechanism of SYT1 in pressure overload-induced cardiac hypertrophy." (PMID 40279007, 2025). "Transverse aortic constriction (TAC) surgeries were performed to induce cardiac hypertrophy in global Syt1 knockout (Syt1+/−) mice and C57BL/6J wild-type (WT) littermates in vivo, with respective sham mice as negative controls." (PMID 40279007, 2025). "To explore whether SYT1 was pathologically relevant to cardiac hypertrophy, we executed the animals and examined the mRNA and protein expression levels of SYT1 in the LV tissues of mice respectively at 1, 2, 4, and 8 weeks after TAC." (PMID 40279007, 2025). "The study suggests that targeting SYT1 may have clinical perspectives in the treatment of cardiac hypertrophy." (PMID 40279007, 2025). "From this point, exploring the role of SYT1 in cardiomyocyte apoptosis may clarify its role in myocardial hypertrophy." (PMID 40279007, 2025). "However, whether SYT1 affects cardiac hypertrophy by regulating the MAPK signaling is unknown." (PMID 40279007, 2025). "Knocking out SYT1 in vivo or silencing SYT1 in vitro respectively exacerbated TAC- or Ang II-induced cardiac injury including cardiac hypertrophy, fibrosis, dysfunction and cardiomyocyte hypertrophy and apoptosis, suggesting a protective role of SYT1 in cardiac hypertrophy." (PMID 40279007, 2025). "Notably, we found that heterozygous SYT1 KO alone could not induce cardiac hypertrophy." (PMID 40279007, 2025).
cutaneous melanoma (1 paper, 2024). A primary melanoma arising from atypical melanocytes in the skin. "Moreover, the activation of Golgi Arf-like protein 1 (ARL1) is facilitated by synaptotagmin 1 (SYT1), with ARL1 independently serving as a prognostic determinant for cutaneous melanoma, as higher ARL1 levels correspond to improved prognosis." (PMID 38365684, 2024).
diabetic encephalopathy (1 paper, 2025). A brain disease that is characterized by functional impairment of cognition, cerebral signal conduction, neurotransmission and synaptic plasticity, and underlying structural pathology associated with diabetes. "Both the mRNA and the protein levels of Syt1 were decreased during oxidative stress induced by advanced glycation end-products (AGEs) in diabetic encephalopathy." (PMID 39865120, 2025).
Epileptic encephalopathy (1 paper, 2024). A condition in which epileptiform abnormalities are believed to contribute to the progressive disturbance in cerebral function. "We studied three mutations in SNAP25 that cause epileptic encephalopathy: V48F, and D166Y in the synaptotagmin-1 (Syt1)-binding interface, and I67N, which destabilizes the SNARE complex." (PMID 38411501, 2024).
haemorrhoid (1 paper, 2020). "However, the results showed that the expression levels of all important node genes (CLTA, CLTC, RAB3A, SNAP25, SYT1, VAMP2) on Synaptic vesicle cycle pathways from haemorrhoid patient samples were lower significantly than them from healthy tissue samples." (PMID 32620169, 2020).
hippocampal atrophy (1 paper, 2024). "In this study, to further confirm our previous findings that reduced synaptic proteins in EVs are associated with the development of AD, we examined the relationship between concentrations of SNAP25, GAP43, neurogranin, and synaptotagmin 1 and degrees of hippocampal atrophy in patients with AD." (PMID 38528511, 2024).
insulinoma (1 paper, 2025). "Syt1 is also expressed in mouse islets tissues, insulinoma cell lines, mast cells from mucosal and connective tissues." (PMID 39865120, 2025).
ischemia (1 paper, 2023). A hypoperfusion of the BLOOD through an organ or tissue caused by a PATHOLOGIC CONSTRICTION or obstruction of its BLOOD VESSELS, or an absence of BLOOD CIRCULATION. "The downregulation of synaptotagmin-1, complexin-1, and neurofilament light polypeptide is likely to reflect degenerative changes following ischemia and is in line with the observed downregulation of the phototransduction cascade." (PMID 37175625, 2023).
leukemia (1 paper, 2014). A malignant (clonal) hematologic disorder, involving hematopoietic stem cells and characterized by the presence of primitive or atypical myeloid or lymphoid cells in the bone marrow and the blood. "The identification of ∼600 bp of a RAS related leukemia viral oncogene (LOC642550) proximal to the L1 retrotransposon within the NAV3 -SYT1-PAWR gene cluster is also of interest given the known and shared role of rearrangement mediated FUS gene fusions between myxoid liposarcoma and leukemia." (PMID 24505276, 2014).
lymph node metastasis (1 paper, 2023). "We further found that SYT1 expression level was negatively correlated with advanced tumor stage, cervical lymph node metastasis, and advanced clinical stage, suggesting that SYT1 may exert a repressing effect on CRC occurrence and development." (PMID 37958455, 2023).
medullary thyroid cancer (1 paper, 2019). "In sporadic medullary thyroid cancer, proteomic analysis and Western blots show abnormal expression of SYT1." (PMID 31391849, 2019).
metastatic tumors (1 paper, 2023). "Consistently, high-metabolism lesions (concentration of 18F-FDG) indicative of metastatic tumors were found in the lungs and livers of the control mice, whereas no obvious concentration of 18F-FDG was found in the SYT1-overexpressing mice." (PMID 37958455, 2023).
migraine (1 paper, 2021). "Therefore, we aimed to further investigate the role and interaction of NRXN2, SYT1, GABRE and CASK, additional components involved in the control mechanisms of neurotransmitter release apparatus in migraine susceptibility." (PMID 34126933, 2021).
nasopharyngeal carcinoma (1 paper, 2024). A carcinoma arising from the nasopharyngeal epithelium. "The study found a correlation between SYT1 and response to radiation therapy for nasopharyngeal carcinoma." (PMID 39593730, 2024).
Oppositional defiant disorder (1 paper, 2022). An enduring pattern of uncooperative, defiant, and hostile behavior towards authority figures that does not involve major antisocial violations, is not accounted for by the child's developmental stage, and results in significant functional impairment. "The authors found that only SYT1-rs2251214 was associated with both short-term response to MPH and the amelioration of inattention and oppositional defiant disorder symptoms." (PMID 36294881, 2022).
psychosis (1 paper, 2019). "Because of the symptoms of psychosis with hypothetically overactive synapses, we examined synaptotagmin-1 MPs, which were also increased, indicating a dysfunction of synaptic vesicular trafficking." (PMID 30696485, 2019).
Sandhoff disease (1 paper, 2025). A lysosomal disorder from the GM2 gangliosidosis family, caused by biallelic pathogenic variants in the HEXB gene, characterized by GM2 ganglioside accumulation in the nervous system and progressive central nervous system degeneration. "Similarly, the increase in abundance of SYT1 in these models of Tay–Sachs and Sandhoff diseases is likely to significantly impact synaptic signalling." (PMID 40608809, 2025).
synovial sarcoma (1 paper, 2016). "Although the SSX family of genes normally functions as suppressors, when SSX1 is fused to SYT1 in the SYT1-SSX1 gene in synovial sarcoma, the fused gene is capable of increasing the expression of both cyclin A and D1." (PMID 27649156, 2016).
tuberculosis (1 paper, 2021). A chronic, recurrent infection caused by the bacterium Mycobacterium tuberculosis. "In antiretroviral therapy, rs199650082 of nucleus signaling-1 (ERN1) is significantly related to DILI, while in antiretroviral therapy combined with anti-tuberculosis therapy, transcriptional variation of synaptotagmin 1 (Syt1) rs4842407 is associated with DILI." (PMID 34552491, 2021).
neurodevelopmental disorder (21 papers, 2018 to 2026). A behavioral and cognitive disorder with onset during the developmental period that involves impaired or aberrant development of intellectual, motor, or social functions. "The precise pathogenic mechanism of SYT1‐associated neurodevelopmental disorders is still unclear, with preliminary data favoring a dominant‐negative effect." (PMID 41438914, 2025). "Previously, physiological phenotypes of other de novo mutations in SYT1-associated with neurodevelopmental disorder have been studied." (PMID 38321119, 2024). "Recently, additional neurodevelopmental disorder-associated SYT1 variants have been identified, both within the critical C2B domain as well as the facilitatory C2A domain of the protein, but a pathogenic mechanism for these variants is yet to be established." (PMID 39481209, 2024). "Developing in vivo animal models harbouring neurodevelopmental disorder-associated SYT1 variants will be key to understanding how these affect whole-brain, network-based systems." (PMID 39481209, 2024). "Disruption toSYT1 is associated with neurodevelopmental disorders, highlighting the importance of identifying high-quality research reagents to enhance understanding of Synaptotagmin-1 in health and disease." (PMID 39169954, 2024). "Together, this suggests that there is a genotype-function-phenotype relationship in SYT1-associated neurodevelopmental disorder, centring impaired evoked neurotransmitter release as a common pathogenic driver." (PMID 39481209, 2024). ",29,34[preprint] We reveal here a shared mechanism of pathogenicity that correlates with core neurodevelopmental features of SYT1-associated neurodevelopmental disorder." (PMID 39481209, 2024). "We have focused our study on a limited range of phenotypes that we have previously detailed to be prevalent in SYT1-associated neurodevelopmental disorder, and for which quantitative measures were available." (PMID 39481209, 2024). "This is a novel cellular phenotype, distinct from what was previously found for other SYT1 disease variants, and points to a role for spontaneous and asynchronous release in SYT1-associated neurodevelopmental disorder." (PMID 38321119, 2024). "This establishes impairment of evoked neurotransmitter release as a likely candidate mechanism constraining the development of cognitive and motor abilities, leading to core features of SYT1-associated neurodevelopmental disorder." (PMID 39481209, 2024). "Nevertheless, the strong correlations observed between exocytic efficiency and severity of adaptive impairments support disruption to evoked neurotransmitter release as a primary pathogenic mechanism underlying SYT1-associated neurodevelopmental disorder." (PMID 39481209, 2024). "In 2015, the first cases of neurodevelopmental disorders caused by pathogenic Syt-1 variants were reported in two patients harboring I368T and M303K variants." (PMID 37066095, 2023). "Variants in the SYT1 gene give rise to a neurodevelopmental disorder, also known as Baker-Gordon syndrome (OMIM 618218), that commonly presents with infantile hypotonia, developmental delay, ID, ophthalmic abnormalities, and movement disorders." (PMID 37066095, 2023). "In 2021, the phenotypic spectrum of Syt1-associated neurodevelopmental disorder was expanded, upon identification of various novel pathogenic (or likely pathogenic) variants, including the ones in the C2A domain." (PMID 37066095, 2023). "Neurodevelopmental disorder–associated SYT1 variants extend beyond previously reported regions, and the phenotypic spectrum encompasses a broader range of severities than initially reported." (PMID 35101335, 2022). "C2B domain is the main site of mutations associated with SYT1-associated neurodevelopmental disorder." (PMID 36291375, 2022). "The first variant discovered that prompted the classification of SYT1-associated neurodevelopmental disorder was I368T in 2015." (PMID 36291375, 2022).